IL17A (interleukin 17A)
Diseases named in the same sentence as IL17A in open-access papers (continued):
Sharing a sentence is not in itself a finding about the gene and the disease.
asthma (continued). "This would enable higher responses to low levels of IL-17A, IL-4 and IL-13 and thus contribute to more marked inflammatory effects such as those seen in severe asthma." (PMID 25849622, 2015). "More recently, we showed that blood T-cell IL-17A expression was increased 7-fold in patients with SR asthma compared with that seen in patients with SS asthma." (PMID 25772594, 2015). "In agreement with the presence of these endpoints in asthma, increased levels of IL-17A, IL-17F and IL-22 are found at the circulating and lung levels in allergic asthmatic patients as compared with controls." (PMID 25860963, 2015). "Th17 cytokines which included IL-17A, IL-17F, and IL-22 elevated obviously in asthma group compared to NC group (p < 0.05), and acupuncture exerted inhibitory effect on these cytokine levels (p < 0.05)." (PMID 26612993, 2015). "The presence of IL-22 and IL-17A in the sputum or peripheral blood is positively correlated with the severity of asthma." (PMID 26150907, 2015). "Acupuncture reduced the OVA specific IgE level as well as the Th17 cytokine levels including IL-17A, IL-17F, and IL-22 in the serum of the experimental asthma mice." (PMID 26612993, 2015). "Cells from the patients with SR asthma compared with those from the patients with SS asthma continued to show increased mean production of IL-17A and IFN-γ across a range of dexamethasone concentrations." (PMID 25772594, 2015). "Oral calcitriol, compared with placebo, therapy of the patients with SR asthma significantly improved dexamethasone-induced IL-10 production in vitro while suppressing dexamethasone-induced IL-17A production." (PMID 25772594, 2015). "In addition, severe asthma phenotypes may be associated with the presence of Th17 cells, and the production of a Th17 profile (IL-17A, IL-17 F, IL-22, and IL-21) and IL-1β, which was shown to induce a Th17 profile and induces an increase in airway inflammation predominantly within neutrophil cells." (PMID 27965764, 2015). "The experimental asthma mice had higher CD4+IL-17A+ cell numbers and decreased CD4+Foxp3+ cell numbers in BALF as compared to NC mice (p < 0.01)." (PMID 26612993, 2015). "IL-17A promotes the migration of asthma patient-derived smooth muscle cells through p38-MAPK signalling pathways." (PMID 25551434, 2014). "In obesity-associated asthma, the development of airway hyperreactivity (AHR) is thought to be dependent on IL-17A and the NLRP3 inflammasome." (PMID 25128964, 2014). "Obese mice exhibit innate airway hyperresponsiveness (AHR), a characteristic feature of asthma, and IL-17A is required for development of AHR in obese mice." (PMID 25309539, 2014). "Because the level of IL-17A in BALF was increased in the asthma group mice and anti-HMGB1 IgG treatment suppressed it, we examined the possibility that this suppression was mediated through the decreased production of Th17 cells in the lung." (PMID 24959003, 2014). "Human studies have shown increased expression of IL-17A and IL-17F in bronchial submucosa in moderate to severe asthma." (PMID 25177863, 2014). "Studies have shown that, in a mouse model of asthma, dexamethasone inhibited gene expression of IL-17A and alleviated the exacerbation of the inflammatory process induced by IL-17A." (PMID 24744681, 2014). "In cultured T-lymphocytes IL-17A and RORγ(t) expression were higher in mild-moderate asthma/persistent rhinitis than in mild-moderate asthma/intermittent rhinitis, while FOXP3 was reduced." (PMID 23573194, 2013). "On the other hand, IL-17A is a proinflammatory cytokine playing a very important role in the induction and propagation of inflammation in asthma." (PMID 23573194, 2013). "Bronchoalveolar lavage fluid (BALF) from asthma patients contains high amounts of IL-4/IL-17A double-positive CD4+ T cells, and moderate-to-severe human asthma patients have more IL-17A-positive cells in bronchial submucosa than mild asthma patients." (PMID 23383714, 2013).
asthma (continued). "Studies to unravel the role of IL-17A in asthma started in the late nineties by expression studies in airway cells." (PMID 23401702, 2013). "In humans, increased expression of IL-17A and IL-17F was detected in bronchial submucosa, and examination of sputum in patients with asthma demonstrated that neutrophils were present, particularly in severe forms of this disease." (PMID 23956763, 2013). "In a model of RSV-promoted asthma exacerbation, IL-17A-/- mice exhibited increased AHR despite a decrease in neutrophils, demonstrating a protective role for IL-17A." (PMID 24069338, 2013). "We here review the role of IL-17A and neutrophil recruitment in several human respiratory diseases: asthma, COPD, CF, and lung transplant rejection." (PMID 23401702, 2013). "We analyzed the IL-17A levels in sputum supernatants (Ss), nasal wash (NW) and plasma (P) from Healthy Controls (HC) and children with Asthma/Rhinitis." (PMID 23573194, 2013). "Since some phenotypes of asthma cannot be explained using classical Th1/Th2 theory, numerous recent studies have suggested possible roles of IL-17A and IL-17F in asthma." (PMID 24454477, 2013). "Elevated concentrations of IL-17A were found in allergic asthma patients, and this finding was correlated with the severity of asthma." (PMID 23533467, 2013). "IL-17A was shown to be expressed in bronchial biopsies, bronchoalveolar lavage fluid and sputum of patients with asthma." (PMID 23401702, 2013). "Whole peripheral blood cells from non-asthmatic control subjects (n = 17) and patients with mild asthma (n = 7), moderate but persistent asthma (n = 4), or acute asthma (n = 6) were analyzed for IL-17A expression in CD177+ neutrophils." (PMID 23822853, 2013). "IL-17A was increased in Ss, NW and P from children with mild-moderate asthma compared with intermittent and HC." (PMID 23573194, 2013). "IL-17A has been considered as one of most important player in asthma, however, clinical attempts for anti-IL-17A therapy to asthma has just begun." (PMID 24032029, 2013). "Further studies are certainly warranted to investigate the molecular mechanisms responsible for this, as well as the impact of other cytokines expressed in severe asthma, such as IL-17A, on the ability of bronchial epithelial cells to progress through EMT." (PMID 24283210, 2013). "We also observed an increase of CD4+IL-17+ T cells in acute asthma, reinforcing the importance of IL-17A in the immunopathology of asthma." (PMID 23822853, 2013). "Apart from the contribution to neutrophilic inflammation in asthma, IL-17A is also suggested to be responsible for the eosinophilia observed in the airways of asthmatic patients." (PMID 22855687, 2012). "Administration of rapamycin prior to the induction of asthma significantly inhibited lung mRNA levels of canonical Th2 (IL-4 and IL-13) and Th17 (IL17A) cytokines." (PMID 22685525, 2012). "Treg cells are also known to inhibit IL-17a production, which is a strong pro-inflammatory cytokine that plays an important role in airway inflammation in asthma patients." (PMID 23091602, 2012). "Taken together, there are several alternatives to regulate IL-17A expression representing new therapeutic strategies in the treatment of asthma." (PMID 22855687, 2012). "According to that, we chose the three cytokines, transforming growth factor β (TGF-β), IL-10, and IL-17A for further discussion, focusing on their effects on asthma as well as on lung tumor and their relevance as possible therapeutic targets." (PMID 22855687, 2012). "The involvement of a mixed Th2/Th17 cytokine profile in asthma pathogenesis is supported by human studies showing increased production of IL-17A and infiltration of Th17 cells in the lungs of asthmatics, particularly those with more severe disease." (PMID 19060952, 2008). "Sputum IL-17A and IL-8 mRNA levels are significantly elevated in asthma patients compared to healthy controls." (PMID 17083726, 2006).
asthma (continued). "High IL-17A and/or IL-8 mRNA levels were always found in patients with moderate/severe asthma while only approximately half of the mild asthmatics had increased IL-17A and/or IL-8 mRNA levels in their sputum." (PMID 17083726, 2006). "High IL-17A and/or IL-8 mRNA levels were found in patients with moderate-to-severe asthma, even if those patients were treated with corticosteroids." (PMID 17083726, 2006). "IL-8 mRNA levels were higher in patients with moderate-to-severe asthma than in patients with mild asthma, whereas IL-17A mRNA levels were similarly elevated in both subgroups." (PMID 17083726, 2006). "Interleukin 17A (IL‐17A) can activate a range of inflammatory cascades that mediate the development and progression of periodontitis along with related systemic chronic inflammatory diseases like asthma." (PMID 39811802, 2025). "Given that IL-17A is associated with neutrophilic inflammation, these findings suggest a participation of SCF in IL-17A production and neutrophilic inflammation during asthma." (PMID 40674143, 2025). "Moreover, IL-17A enhances airway smooth muscle contractility, migration, and proliferation, thereby contributing to AHR and airway remodeling—hallmark features of asthma." (PMID 41515904, 2025). "The data indicate that in patients with TH2-mediated asthma, extrinsic factors inducing IL-17A secretion may intensify neutrophilic inflammation and IL-8 secretion, consequently worsening lung pathology and progressing to ALI." (PMID 40872499, 2025). "Activation of the NLRP3 inflammasome in the lungs not only facilitates the infiltration and activation of neutrophils, but also promotes the expansion and activation of ILC3s and IL17A secretion, which contribute to exacerbated asthma symptoms and increased steroid resistance." (PMID 40329860, 2025). "Similarly to the evidence on COPD, Th17 cells and the cytokines they produce (IL-17A and IL-17F) seem to have a role in the pathophysiology of severe and steroid-resistant asthma." (PMID 40136649, 2025). "We found that SCF expression was increased in the plasma, blood, and sputum samples from asthmatic patients and positively correlated to IL-17A and MPO expression, suggesting that SCF is associated with IL-17A production and neutrophilic inflammation during asthma." (PMID 40674143, 2025). "Notables such as secukinumab (an IL-17A monoclonal antibody) and brodalumab (an IL-17 receptor antagonist) have shown potential in clinical trials, particularly in individuals with neutrophilic and corticosteroid-resistant asthma." (PMID 40564060, 2025). "Th17 cells produce cytokines IL-17A and IL-17F, and the heterodimer IL-17A/F is a critical pro-inflammatory cytokine that is elevated in neutrophilic airway inflammation during respiratory disease such as severe asthma." (PMID 40410820, 2025). "This indicates that the herb pair may alleviate airway vascular remodeling and mucosal congestion in severe asthma by intervening in IL-17 A/F release mediated by Th17 cells." (PMID 40605076, 2025). "When we tested for nutrients associated with proinflammatory cytokines, FAs showed the most prominent negative associations with IL-2, IL-10, IL-13, and IL-17A, which play key roles in the inflammatory processes underlying asthma." (PMID 41256924, 2025). "Additionally, estrogen enhances IL-17A-mediated airway inflammation, which is more pronounced in females with severe asthma compared to males." (PMID 40508095, 2025). "Notably, poly(I:C)-mediated TLR3 activation of NK cells stimulates IL-17A production, leading to asthma exacerbation." (PMID 40355861, 2025). "In summary, the present results demonstrate that stigmasterol have anti-inflammatory effects both locally and systemically, reduces the excessive production of Th 17 cells in the body, increases IL-10 levels and down-regulates IL-17A levels, to improve the symptoms of asthma in mice." (PMID 38579176, 2024).
asthma (continued). "Children with asthma had higher levels of IL-2 (p = 0.005), IL-5 (p < 0.001), IL-13 (p = 0.021), IL-17A (p < 0.001), IL-22 (p < 0.001), IL-33 (p < 0.001), TNF-α (p < 0.001), and lower levels of IL-10 (p = 0.046) and leptin (p < 0.001) compared to those without asthma." (PMID 39902293, 2024). "Furthermore, we observed upregulation of IL-17A in the lung of Dectin-1-activated asthma mice, an effect that was suppressed by caspase-11 inhibitors." (PMID 38459541, 2024). "Additionally, wedelolactone inhibited the IL-1α, IL-1β, IL-6 and IL-17a mRNA expression, which were related to neutrophilic predominant asthma." (PMID 38459541, 2024). "In cases of asthma characterized by an imbalance in Th17/Treg immune response, Chinese medicine has been shown to impact eosinophilic asthma by reducing levels of cytokines such as IL-17A, INF-γ, TGF-β, and ROR-γ." (PMID 39411430, 2024). "Our study provides key evidence that excessive activation of the TGF-β/Smad pathway may lead to overproduction of IL-17A in OVA-induced asthma." (PMID 38579176, 2024). "Initial animal studies suggested that treatment with anti-IL-17A could decrease pulmonary inflammation, edema, oxidative stress, and remodeling in a model of LPS-exacerbated asthma." (PMID 39194521, 2024). "In addition, obesity and asthma showed a significant interaction effect on the plasma levels of IL-5, IL-10, IL-17A, IL-33, TNF-α, and leptin." (PMID 39902293, 2024). "Therefore, in the present study, we investigated the SNPs in asthma disease and measured the serum concentrations of total IgE and IL-17A." (PMID 38660682, 2024). "Furthermore, the increased expression of IL-17A has been correlated with severe asthma in humans, with increased neutrophilic infiltrates evident in mucus." (PMID 38783005, 2024). "These immunological markers may correspond to pathophysiological characteristics of asthma: periostin, IgE, IL-5, and IL-33 for T2 asthma; IL-6, IL-8, IL-17A, and IL-33 for non-T2 asthma." (PMID 38256660, 2024). "In addition to TH2 cells, TH17 cells and their produced cytokine IL-17A are prominent and extensively studied in the context of asthma, particularly in severe, steroid-resistant cases." (PMID 39439788, 2024). "Currently, several scientific reports have found that the TGF-β/Smad signaling pathway also regulates the differentiation process of Th17 cells, suggesting that inhibiting IL-17A may be an effective anti-asthma avenue." (PMID 38579176, 2024). "Compared with OVA sensitization or hyperoxia exposure alone, the mice in the model group (O2+OVA) showed asthma-like symptoms and increased airway hyperreactivity,The levels of IL-5,IL-13 IL-17A were increased in BLAF,and total leukocyte and eosinophil counts were also significant increasesed." (PMID 38148813, 2024). "In addition, many reports identified that levels of IL-17A are correlated positively with the severity of asthma." (PMID 36902294, 2023). "According to multiple research, children, and adults with obesity-associated asthma had higher peripheral blood levels of IL-17A, IL-21, and TNF-α than non-obese patients." (PMID 37377958, 2023). "Taken together, our findings indicate that IL-17A-enriched NETs, induced by the asthma microenvironment, may promote the HELFs’ dysfunction, switching them to a pro-fibrotic state." (PMID 37626601, 2023). "Th17 cells produce IL-17A, IL-17F, IL-21, IL-22, and TNF-α to perform their functions, and IL-17A and IL-17F are linked to severe asthma with neutrophil inflammation and responsible for corticosteroid resistance in asthma." (PMID 38203353, 2023). "Moreover, TGFβ correlates with increased TH17 activity in patients with severe asthma and is essential for IL-17A production." (PMID 37443808, 2023). "While working, we have also found that the AA genotypeof IL17A rs2275913, the TT genotype of IFNG rs2069705,and the A allele of TNFA rs1800629 were associated withmild asthma, and the TT genotype of IFNG rs2069705 – withcontrolled asthma." (PMID 37465198, 2023).
asthma (continued). "Notably, IL-17A induces GR-β expression in the airway epithelium of patients with asthma and generates steroid resistance in peripheral blood mononuclear cells, resulting in SRA." (PMID 37920459, 2023). "Moreover, the relationship between serum IL-17A levels and other allergic diseases, such as asthma, allergic rhinitis (AR), and atopic dermatitis (AD), has been shown." (PMID 38090557, 2023). "The findings suggest that in individuals with TH2-mediated asthma, additional stimuli triggering IL-17A production may contribute to heightened neutrophilic inflammation and IL-8 production, potentially exacerbating lung pathology." (PMID 37443808, 2023). "Indeed, we found that asthma-serum-treated control neutrophils efficiently generated IL-17A-enriched NETs, as indicated via the immunofluorescence microscopy and IL-17A ELISA on isolated NETs." (PMID 37626601, 2023). "Neutralization of IL-17A in OVA asthma leads to a decrease in neutrophil granulocytes in the BAL." (PMID 37443808, 2023). "The ability of gut microbiota to influence interleukin-17A (IL-17A) may be particularly relevant to obesity-related asthma." (PMID 38292857, 2023). "IL-17A was also found to be elevated in obesity-related asthma patients." (PMID 38292857, 2023). "In conclusion, we identified epithelial SIRT6 to be an important positive regulator of IL-17A secretion in severe asthma, in which it positively regulated airway inflammation and remodeling mainly throug IL-17A-mediated inflammatory chemokines and mesenchymal reprogramming." (PMID 38135684, 2023). "lncRNA CRNDE expression downregulation led to reduced inflammation and reduced lung damage in mice with induced asthma, it inhibited the EMTs of lung epithelial cells via the miR-29a-3p/MCL-1 pathway, and it reduced the levels of Th17/IL-17A cells to reduce asthma signs." (PMID 36743692, 2023). "Our findings assess that asthma NETs, released upon the stimulation of control neutrophils with the inflammatory disease microenvironment, are enriched with IL-17A, indicating a possible link between this pro-inflammatory cytokine and childhood asthma pathogenesis." (PMID 37626601, 2023). "Together, these data support the therapeutic hypothesis that blocking SIRT6 could prevent IL-17A-mediated airway inflammation and remodeling in severe asthma." (PMID 38135684, 2023). "Thus, our study disclosed a role for SIRT6 in regulating IL-17A pathogenicity in severe asthma, implicating SIRT6 as a potential therapeutic target for severe asthma." (PMID 38135684, 2023). "Therefore, the levels of IL-17A were evaluated in the sera of asthma patients using an ELISA assay and were found to be markedly increased in the patient group compared to the control group." (PMID 37626601, 2023). "Neutrophilic asthma exhibits significant steroid resistance and IL-17A dependence." (PMID 37920459, 2023). "Given that the pathogenesis of neutrophil-driven disorders is essentially determined by the protein composition of NETs, we then tested whether IL-17A is externalized on NETs, formed by control neutrophils, upon treatment with asthma serum." (PMID 37626601, 2023). "In the asthma mouse model, IL-17A induced increased airway neutrophil infiltration." (PMID 36743692, 2023). "Since the increased expression of IL-17A in asthma patients has been attributed to T cells that were later described as Th17 cells, this non-T2 asthma endotype has also been termed Th17-high asthma." (PMID 35883573, 2022). "IL-17A is more highly expressed in severe asthma patients than in mild-to-moderate asthma patients and could be a driver of neutrophilic inflammation in the asthmatic airway." (PMID 35602900, 2022). "Why this assessment was omitted remains elusive and leaves the possibility that an anti-IL-17A-directed therapeutic approach still could provide beneficial effects in those severe asthma patients that display an IL-17/Th17 high endotype." (PMID 35883573, 2022).